COQ10A (coenzyme Q10A)
Description:
Required for the function of coenzyme Q in the respiratory chain. May serve as a chaperone or may be involved in the transport of Q6 from its site of synthesis to the catalytic sites of the respiratory complexes (Probable).
Synonyms: FLJ32452
Tractability: Antibody: UniProt places it where antibodies can reach, with medium confidence. PROTAC: its protein half-life has been measured.
Gene: Protein-coding gene on chromosome 12 (56,266,846 to 56,270,966, forward strand). Ensembl gene ENSG00000135469.
Subcellular location: Mitochondrion inner membrane
Subcellular location (Human Protein Atlas): Cytosol; Endoplasmic reticulum; Golgi apparatus
Pathways (Reactome):
Metabolism: Complex IV assembly; Respiratory electron transport
Gene Ontology:
Molecular function: ubiquinone binding
Biological process: cellular respiration
Cellular component: mitochondrion; mitochondrial inner membrane
Genetic constraint (gnomAD): Loss-of-function variants: 23 observed, 21.35 expected, observed/expected ratio (o/e) 1.08, 90% interval 0.77 to 1.52. The upper end of that interval is the gene's LOEUF score, 1.52, which puts it in group 6 of 6, group 1 being the genes least tolerant of losing a copy. Missense variants: 305 observed, 314.84 expected, observed/expected ratio (o/e) 0.97, 90% interval 0.88 to 1.07. Synonymous variants: 130 observed, 113.42 expected, observed/expected ratio (o/e) 1.15, 90% interval 0.99 to 1.33.
Homologues: Orthologues: chimpanzee COQ10A (99% identical), rabbit COQ10A (92% identical), mouse Coq10a (91% identical), rat Coq10a (90% identical), pig COQ10A (89% identical), dog COQ10A (89% identical), guinea pig COQ10A (82% identical), zebrafish coq10a (63% identical), tropical clawed frog coq10a (63% identical), macaque COQ10A (61% identical), Drosophila melanogaster CG9410 (36% identical), Caenorhabditis elegans R144.13 (29% identical). Paralogues in human: COQ10B (61% identical).
Diseases named in the same sentence as COQ10A in open-access papers:
COQ10A is named in the same sentence as 6 diseases in open-access papers, as found by Europe PMC text mining. Sharing a sentence is not in itself a finding about the gene and the disease. The quoted sentences say what the papers report.
myasthenia (1 paper, 2025). "We performed an enzyme immunoassay of plasma to compare the concentration of proteins: COQ10A, GAPDH1, and SDHC in patients with myasthenia compared to controls." (PMID 40843740, 2025).
myasthenia gravis (1 paper, 2025). Myasthenia gravis (MG) is a rare, clinically heterogeneous, autoimmune disorder of the neuromuscular junction characterized by fatigable weakness of voluntary muscles. "Our data suggest hsa-miR-148a-3p and hsa-miR-194-5p, as well as COQ10A, as potential biomarkers of mitochondrial dysfunction in myasthenia gravis." (PMID 40843740, 2025). "We conducted a study of plasma expression of microRNA hsa-miR-181a-5p, hsa-miR-194-5p, and hsa-miR-148a-3p, as well as three proteins—COQ10A, GAPDH1, and SDHC—in patients with an established diagnosis of myasthenia gravis in comparison with healthy volunteers." (PMID 40843740, 2025).
psoriasis (1 paper, 2022). An autoimmune condition characterized by red, well-delineated plaques with silvery scales that are usually on the extensor surfaces and scalp. "COQ10A is upregulated in CAD (FC = 3.76, p = 2.4 × 10−3), while IL23A is upregulated in psoriasis (FC = 6.91, p = 1.8 × 10−10)." (PMID 36323703, 2022).
Sepsis (1 paper, 2025). Sepsis is defined as life-threatening organ dysfunction caused by a dysregulated host response to infection. "We identified COQ10A as biomarkers for sepsis, which showed significantly lower expression levels in patients with sepsis." (PMID 40421007, 2025). "Four biomarkers (YME1L1, ECHDC3, THEM4, and COQ10A) related to mitochondrial and macrophage polarization in sepsis were obtained by differential expression, machine learning, and expression validation." (PMID 40421007, 2025). "Among them, YME1L1, THEM4, and COQ10A showed significantly lower expression levels in sepsis samples, while ECHDC3 exhibited markedly higher expression." (PMID 40421007, 2025). "Therefore, machine learning and gene expression analysis were utilized in this study to identify YME1L1, ECHDC3, THEM4, and COQ10A as biomarkers for sepsis in our study." (PMID 40421007, 2025). "Notably, RT-qPCR analysis confirmed that YME1L1, THEM4, and COQ10A exhibited significantly lower expression levels in sepsis samples." (PMID 40421007, 2025). "Downregulation of COQ10A may prompt the development of sepsis by inhibition of oxidative phosphorylation." (PMID 40421007, 2025). "Subsequent gene expression analysis revealed that YME1L1, THEM4, and COQ10A exhibited significantly lower expression levels in sepsis patient samples from both the GSE95233 and GSE28750 datasets, while ECHDC3 demonstrated markedly higher expression in sepsis patients (p < 0.05)." (PMID 40421007, 2025). "RT-qPCR results showed YME1L1, THEM4, and COQ10A were obviously lower expression in sepsis samples (p < 0.05), while ECHDC3 did not significant differences between sepsis and control samples." (PMID 40421007, 2025). "Consequently, YME1L1, THEM4, COQ10A, and ECHDC3 were identified as biomarkers for sepsis." (PMID 40421007, 2025).
COQ10A also shares sentences with these, for which no sentence is quoted: cancer (1 paper); tumor (1).